THY1 (Thy-1 cell surface antigen)
Diseases named in the same sentence as THY1 in open-access papers (continued):
Sharing a sentence is not in itself a finding about the gene and the disease.
Atrophy (2 papers, 2016 to 2017). Any weakening or degeneration, especially through lack of use. "First, we examined the time-dependent changes in retinal thickness in the eyes of Thy1-GFP rats with ischemic retinal injury by using spectral domain-optical coherent tomography (SD-OCT) images to detect the retinal damage or atrophy caused by ischemic retinal injury." (PMID 28317920, 2017).
Brain atrophy (2 papers, 2023 to 2024). Partial or complete wasting (loss) of brain tissue that was once present. "Here, we show that Thy1-ApoE4/C/EBPβ Tg and 3xTg mice exhibit age-dependent brain atrophy and hippocampal and cortical volume reduction validated by MRI, which are consistent with temporal neuronal cell death in both mice." (PMID 38658772, 2024). "A fifth and final category of changes included the onset of brain atrophy and decreases in neuronal and neurosecretory proteins such as secretogranin-2, VGF, thy1 membrane glycoprotein, and neuropentraxin and its receptor, suggesting frank synaptic and neuronal loss." (PMID 37550416, 2023).
brain cancer (2 papers, 2019 to 2024). A primary or metastatic malignant neoplasm affecting the brain. "Additionally, our studies suggest that the ALDHbright population validates the CSC phenotype based on the increased expression of brain cancer stem cells genes such as ALDH1A1, ITGA6, THY1, PROM1, and SOX2." (PMID 30646520, 2019).
cervical cancer (2 papers, 2016 to 2025). A primary or metastatic malignant neoplasm involving the cervix. "CD90 (Thy-1) and CD147 are additional receptors implicated in HCMV entry into epithelial cells, often showing increased expression in HPV-positive cervical cancer tissues." (PMID 40002177, 2025).
clear cell renal cell carcinoma (2 papers, 2020 to 2024). "In contrast, MSC-2 clusters derived from the bone marrow of patients with clear cell renal cell carcinoma metastases maintained the classic MSC markers NT5E and THY1 (CD90), but the expression of VCAM1, LEPR, and CXCL12 was reduced." (PMID 39156727, 2024).
Duchenne muscular dystrophy (2 papers, 2017 to 2024). Duchenne muscular dystrophy (DMD) is a neuromuscular disease characterized by rapidly progressive muscle weakness and wasting due to degeneration of skeletal, smooth and cardiac muscle. "Furthermore, THY1+ FAPs have been associated with tissue-level fibrosis in the context of denervation, though not in Duchenne muscular dystrophy, in which an Adam12/Mmp19/Postn-expressing subpopulation (without a clear analog in our data set) appears to be a dominant contributor." (PMID 38954467, 2024).
epilepsy (2 papers, 2012 to 2023). A brain disorder characterized by episodes of abnormally increased neuronal discharge resulting in transient episodes of sensory or motor neurological dysfunction, or psychic dysfunction. "Other genes and gene families showing monoallelic expression include the annexin gene family and the Thy1 gene, both linked to inflammation and cancer, as well as genes linked to alcohol dependence (Gabrg1) and epilepsy (Kcnma1)." (PMID 22384067, 2012).
experimental autoimmune encephalomyelitis (2 papers, 2013 to 2021). An autoimmune demyelinating disease of the central nervous system that is produced experimentally in animals by the injection of homogenized brain or spinal cord in Freund's adjuvant. "(A) Relative qPCR mRNA expression in hippocampal primary neuronal cultures (hPNC) (DIV14) of wild-type (n = 4) and Thy1-Ppargc1a (n = 4) mice of Ppargc1a-regulated electron transport chain genes that were detected to be downregulated during experimental autoimmune encephalomyelitis." (PMID 33565962, 2021). "Finally, there is compelling evidence of mitochondrial dysfunction from in vivo imaging of double-transgenic mice with CFP-labeled mitochondria and YFP-labeled axoplasm (Thy1-MitoCFP × Thy1-YFP-16) induced with experimental autoimmune encephalomyelitis (EAE), a commonly used animal model for MS." (PMID 23898299, 2013).
frontotemporal dementia (2 papers, 2018 to 2024). Frontotemporal dementia (FTD) comprises a group of neurodegenerative disorders, characterized by progressive changes in behavior, executive dysfunction and language impairment, as a result of degeneration of the medial prefrontal and frontoinsular cortices. "These transgenic mice overexpress the human 4R/2N tau isoform bearing the P301L mutation under the control of the neuron-specific murine Thy1 promoter with an accumulation of hyperphosphorylated tau, which serves as a transgenic model for AD and frontotemporal dementia (FTD)." (PMID 39594520, 2024). "In agreement with our results, a robust neuroinflammatory response characterized by microgliosis has been described in the mouse model expressing human P301S mutated tau protein under the control of the Thy1 promotor and in patients with frontotemporal dementia carrying the P301S mutation." (PMID 30487735, 2018).
Graves ophthalmopathy (2 papers, 2012 to 2025). An autoimmune disorder of the EYE, occurring in patients with Graves disease. "Furthermore, in line with the characteristic markers and the evolutionary pattern observed in the pathogenic subcluster of thyroid-associated ophthalmopathy (TAO), apoptotic fibroblasts, the only Thy-1(CD90)− subcluster, possessed a strong capacity to differentiate into adipocytes." (PMID 40001256, 2025).
heart failure (2 papers, 2014 to 2023). Inability of the heart to pump blood at an adequate rate to meet tissue metabolic requirements. "In an experimental model for cardiac hypertrophy and heart failure, Thy-1-negative ventricular fibroblasts accumulated and displayed a more activated, pro-fibrotic myofibroblast phenotype compared to Thy-1-positive cells." (PMID 36768219, 2023).
Hepatitis (2 papers, 2013 to 2019). Inflammation of the liver. "Hepatic RORγt+ ILCs were depleted by anti-Thy1 mAb, but not by anti-NK1.1 mAb or anti-asialo GM1 Ab, in the liver of CCl4-administrated RAG-2−/− mice causing a severer hepatitis." (PMID 23626860, 2013).
injury (2 papers, 2014 to 2021). Damage inflicted on the body as the direct or indirect result of an external force, with or without disruption of structural continuity. "Previously we determined that senescence increases tissue expression of fibronectin EDA (Fn-EDA) and decreases fibroblast expression of Thy-1, and that fibrocytes contribute to fibrosis following bleomycin-induced lung injury in mice." (PMID 24596659, 2014).
lymphopenia (2 papers, 2021 to 2023). Reduction in the number of lymphocytes. "Analysis of tumor-infiltrating lymphocytes (TILs) indicated that IL7-Fc injection did not increase the transfer of Thy1.1+CD8+ T cells, but increased the infiltration of endogenous Thy1.1−CD8+ T cells in immune-competent mice on day 13; this increase was impaired by inducing lymphopenia." (PMID 34440787, 2021).
Optic neuropathy (2 papers, 2020 to 2021). "Neurofilaments, tubulins, and Thy-1 membrane glycoproteins are specifically expressed by RGCs and are useful for the visualization of surviving RGCs in optic neuropathy." (PMID 34445296, 2021). "By generating a fluorescent GFP reporter iPSC line to follow transplanted cells, we provide evidence that THY1-positive RGCs injected into the vitreous of mice with optic neuropathy can survive up to 1 month, intermingled with the host RGC layer." (PMID 33195235, 2020).
ovarian adenocarcinoma (2 papers, 2015 to 2023). An adenocarcinoma that arises from the ovary. "In ovarian adenocarcinoma patients, THY1 expression is reduced, and THY1 expression is specifically found in the non-tumorigenic cell clones, but not in the tumorigenic ones." (PMID 37046850, 2023).
ovarian tumor (2 papers, 2018 to 2023). "According to the HPA, high expression of CAV2, COL11A1, DNAJB4, THY1 and VCAN decreased the 5-year survival for breast, CNS, colon, kidney, lung and ovarian tumors." (PMID 37986165, 2023).
pancreatitis (2 papers, 2018 to 2021). Inflammation of the pancreas. "Overall, these results showed the clinical potential of Thy1‐targeted microbubbles for a noninvasive and accurate detection of small tumors, based on molecular features that distinguish PDAC from benign conditions such as pancreatitis." (PMID 33532585, 2021). "in vivo imaging of tumors by ultrasound molecular imaging did not enhance imaging signal from the pancreatitis or normal pancreatic tissues but produced four‐ to eight‐fold higher imaging signal intensity in the human Thy1‐positive orthotopic xenograft tumors and transgenic PDAC mouse models." (PMID 33532585, 2021).
primary immunodeficiency (2 papers, 2021 to 2024). "The results demonstrated that genes associated with elevated THY1 expression were notably enriched in primary immunodeficiency and viral protein interaction with cytokine and cytokine receptor." (PMID 39170615, 2024).
retinal degeneration (2 papers, 2013 to 2023). Degeneration of the retina. "This technique, however, limits the time periods from which RGCs can be isolated, missing the earliest born RGCs at which time the greatest stage of axon growth occurs, as well as being limited in its use with models of retinal degeneration as Thy-1 is downregulated following injury." (PMID 37547921, 2023). "The average densities of Thy-1 positive RGCs in rd1 mice did not change over time, and was almost identical to each other between the early stage (3 month-old) and late stage of retinal degeneration (18 month-old) (p>0.05, one-way ANOVA analysis)." (PMID 23840814, 2013).
retinal ischemia (2 papers, 2016 to 2017). A ischemic disease that involves the retina. "In this model, the intraocular pressures of Thy1-green fluorescent protein (GFP) rats were raised to 120 mm Hg for 60 min to induce retinal ischemia." (PMID 28317920, 2017).
thymic tumors (2 papers, 1996 to 2015). "The c-myc proto-oncogene linked to the mouse Thy-1 gene transcriptional unit predisposesmice to development of thymic tumors consisting predominantly of immature CD4+ CD8+cells." (PMID 8924763, 1996).
Wilms tumor (2 papers, 2013 to 2020). An embryonal neoplasm characterized by the presence of epithelial, mesenchymal, and blastema components. "To exclude that the cultured stromal cells represent non-tumorigenic tumour-infiltrating fibroblasts, we obtained pure epithelial and stromal cells from a stromal-type Wilms tumour organoid culture (88T) based on EPCAM (epithelial) or THY1 (CD90, stromal) expression." (PMID 32161258, 2020).
Aortic dissection (1 paper, 2022). Aortic dissection refers to a tear in the intimal layer of the aorta causing a separation between the intima and the medial layers of the aorta. "To further demonstrate the functional crosstalk between dFB2 and SMCs, we isolated dFB2 (THY1+) from specimens of additional Stanford type A aortic dissection patients by FACS, and then collected conditioned medium to culture normal human aortic SMCs (HAVSMCs) for 48 hours." (PMID 34976220, 2022).
asthma (1 paper, 2024). "To identify ILC2-specific SEs, we performed H3K27ac chromatin immunoprecipitation sequencing (ChIP-seq) of lung ILC2s, defined as Lin−CD45+Thy1+ST2+ cells, and lung CD4 T cells in house dust mite-induced asthma models, which recapitulate activated ILC2s and activated Th2 cells in vivo, respectively." (PMID 38969652, 2024).
Ataxia (1 paper, 2023). Ataxia refers to impaired coordination of voluntary muscle movement. "We first observed that some Thy1:SNCA/Snca–/– mice exhibited paralysis and ataxia and then died." (PMID 37898614, 2023).
autism (1 paper, 2025). Persistent deficits in social interaction and communication and interaction as well as a markedly restricted repertoire of activity and interest as well as repetitive patterns of behavior. "We used wide-field calcium imaging to measure neural responses in the olfactory bulb of mouse models of autism using the C57BL/6J-Tg(Thy1-GCaMP6f) GP5.11Dkim/J." (PMID 41062277, 2025).
autonomic dysfunction (1 paper, 2013). "We conclude that Thy1-aSyn mice have impaired basal and dynamic range of sympathetic and parasympathetic-mediated changes in HR and will be a useful model for long-term study of cardiovascular autonomic dysfunction associated with PD." (PMID 23888153, 2013).
bipolar depression (1 paper, 2025). "The THY1 glycoprotein also displayed increased N-glycosylation in individuals with bipolar depression, with 4 glycopeptides enriched at N79." (PMID 40671800, 2025). "Among the identified glycoproteins, Thy1 membrane glycoprotein (THY1) exhibited the highest level of hyperglycosylation in both unipolar and bipolar depression." (PMID 40671800, 2025). "Many shared upregulated glycopeptides in unipolar and bipolar depression were derived from multiple glycosylation sites of NPTN, THY1, CA2D1, and SHPS1 proteins." (PMID 40671800, 2025).
cardiomyopathy (1 paper, 2017). A disease of the heart muscle or myocardium proper. "Analysis of pathways that were dysregulated across cardiomyopathy phenotypes identified shared genes that were associated with extracellular matrix remodeling and thus likely fibrosis (THY1, CILP, OGN, THBS4, ASPN, HAPLN1,and SMOC2), as well as calcium (ADIPOQ, ASPN, THBS4, STAT4, and SMOC2)." (PMID 28098235, 2017).
cholestasis (1 paper, 2021). Impairment of the bile flow caused by obstruction within the liver, or outside the liver in the bile duct system. "In support, simultaneous deletion of Msln and Thy-1 genes yielded a phenotype similar to that in the cholestasis-injured wild type mice, indicating that Msln and Thy-1 might regulate opposing functions within the same signaling pathway." (PMID 34966784, 2021).
cyst (1 paper, 2023). A sac-like closed membranous structure that may be empty or contain fluid or amorphous material. "Conversely, Thy1+ cells that were isolated from GalN-D2 could not differentiate into BECs even in collagen-sandwich culture using the BEC-induction medium, while Thy1+ (GalN-D3) cells could form cord- and/or cyst-like structures." (PMID 38067145, 2023).
demyelination (1 paper, 2020). "Whether these inflammatory cells contribute to the degenerative processes was investigated by the application of our demyelination model on Thy1–CFP//LysM-EGFP mice." (PMID 32655371, 2020).
emphysema (1 paper, 2025). "We found increased expression of vascular markers (Thy1, CD34, and Col4a) in the lung parenchyma of patients with severe emphysema compared with patients with COPD without emphysema or with moderate emphysema." (PMID 39437762, 2025). "Interestingly, Thy1 and Ccl21 were increased in GOLD 1-2 patients with emphysema and prominent TLOs compared with GOLD 1-2 patients without emphysema." (PMID 39437762, 2025).
endometrioid ovarian cancer (1 paper, 2019). "In women with endometrioid ovarian cancer, Thy-1 expression was associated with significantly poorer progression-free survival (upper quartile PFS 11 vs. 34 months, P = 0.013, n = 51)." (PMID 31735168, 2019). "In our bioinformatics analysis, we found that high Thy-1 expression was associated with poorer progression-free survival in both serous and endometrioid ovarian cancers." (PMID 31735168, 2019).
familial Alzheimer disease (1 paper, 2015). A degenerative disease of the brain that causes gradual loss of memory, judgment, and the ability to function socially. "5xFAD mice overexpress (under control of Thy1 promoter) both mutant human APP with the Swedish (K670N, M671L), Florida (I716V), and London (V717I) familial Alzheimer's disease (FAD) mutations and human PSEN1 harboring two FAD mutations (M146L and L286V)." (PMID 25883808, 2015).
Gliosis (1 paper, 2022). Gliosis is the focal proliferation of glial cells in the central nervous system. "We observed substantial amounts of phosphor-tau proteins (AT8) in brain tissues of Thy1-hTau.P301S mice, and these protein accumulations were accompanied by increased expression of GFAP and Iba-1 (markers of astrocytosis and gliosis, respectively) compared with that in wild-type C57 mice." (PMID 36273169, 2022).
hair diseases (1 paper, 2017). "Thus, LNGFR(+)THY-1(+) iMCs may provide material for HF bioengineering and drug screening for hair diseases." (PMID 28220862, 2017).
intestinal motility disorders (1 paper, 2022). "In the present study, we used a transgenic mouse model overexpressing αSyn under the control of the thymus cell antigen 1 (Thy1) promoter to explore the mechanisms underlying the beneficial effects of electroacupuncture on intestinal motility disorders in PD." (PMID 36337584, 2022). "In the present study, we used thymus cell antigen 1-α-synuclein (Thy1-αSyn) transgenic mice as a model of intestinal motility disorders in PD to determine the therapeutic effect of electroacupuncture and the underlying mechanisms." (PMID 36337584, 2022). "In the present study, we showed that electroacupuncture significantly increased the fecal output and accelerated the small-intestine propulsion of Thy1-αSyn mice, thereby improving the intestinal motility disorder." (PMID 36337584, 2022). "The Thy1-αSyn transgenic PD mouse model used in this study is a classic model of intestinal motility disorders in PD." (PMID 36337584, 2022). "Our previous research confirmed that Thy1-αSyn mice had intestinal motility disorders and showed that electroacupuncture downregulated the protein expression of αSyn in the mouse colon tissue and promoted the contraction of colon smooth muscle, thereby improving intestinal motility disorders." (PMID 36337584, 2022).
latent infection (1 paper, 2015). "THY-1 is expressed in many types of cells that can be productively infected by HCMV as well as CD34+/CD38- stem cells, a putative cellular reservoir for latent infection." (PMID 26147640, 2015).
Lewy body disease (1 paper, 2023). "The Thy-1 promoter enables moderate post-natal over-expression of human wild-type alpha-synuclein in all brain regions (including dopamine neurons) and in peripheral neurons, thereby mimicking the expression encountered in sporadic PD and in Lewy body disease in general." (PMID 36715870, 2023). "As observed in PD and in dementia with Lewy bodies patients, methylation of protein phosphatase 2A (PP2A), a process crucial for dephosphorylation of alpha-synuclein, is reduced in Thy1-aSyn transgenics." (PMID 36715870, 2023).
lymph node metastasis (1 paper, 2023). "Our previous studies have identified that THY1 is a tumor suppressor downregulated in NPC via promoter hypermethylation, and such downregulated THY1 expression has been linked to more severe NPC lymph node metastasis." (PMID 37046850, 2023).
male breast carcinoma (1 paper, 2013). A malignant neoplasm involving the male breast. "THY1 may thus be a promising novel prognostic marker for male breast cancer." (PMID 24194916, 2013).
motor neuron degeneration (1 paper, 2016). "Thy1-SNCA transgenic mice express lower levels of α-synuclein than PrP-A53T-SNCA mice and do not show evidence of motor neuron degeneration." (PMID 27126635, 2016).
neuroendocrine tumours (1 paper, 2010). "CD90 (Thy-1) is a neuronal and mesenchymal stem cell marker that also defines the neuronal differentiation of these neuroendocrine tumours." (PMID 20424609, 2010).
ovarian teratoma (1 paper, 2021). A non-seminomatous germ cell tumor arising from the ovary. "RALGPS1 dysfunction might include abnormalities of biogenesis of GPI dependent on the DPM complex and, with any decrease in THY-1, might yield possible clues in pathophysiology of ovarian teratomas." (PMID 34745385, 2021).
overnutrition (1 paper, 2024). An imbalanced nutritional status resulting from excessive intake of nutrients. "In the setting of long-term overnutrition, THBS1 promotes stromal expansion characterized by increased THY1+ FAPs, aberrant ECM deposition, and elevated intramuscular adiposity." (PMID 38954467, 2024).